CCL5 (C-C motif chemokine ligand 5)
Diseases named in the same sentence as CCL5 in open-access papers (continued):
Sharing a sentence is not in itself a finding about the gene and the disease.
tumor (continued). "Exercise-induced elevation of EPI is involved in the regulation of Ccl5 and Cxcl10 levels further leading to enhanced CD8+ T cell infiltration and ultimately inhibiting tumor progression." (PMID 38622609, 2024). "Significantly upregulated expression of CCL5 in ccRCC has been correlated to the EMT and tumor development." (PMID 39169402, 2024). "Treatment with this monoclonal antibody decreased levels of GZMB/CCL5 expressed per CD4+ T cell harvested from T3 or F244 tumour-bearing mice." (PMID 39048822, 2024). "This suggests CCL5 not only remodels the PDAC TME to benefit tumor cells, but can also enhance the tumor cell’s metastatic potential." (PMID 38339310, 2024). "Research has shown that NKs can produce chemokines CCL5 and XCL1 to recruit cDC1 into the tumor microenvironment, which is necessary for tumor immune control, and the disruption of this process can lead to cancer immune escape." (PMID 38339158, 2024). "CCL5 binds with a high affinity to the G-protein-coupled receptor, CCR5, which is upstream of multiple pro-tumor signaling pathways including PI3K/Akt and JAK2/STAT3." (PMID 39409924, 2024). "TAMs are usually dependent on chemokines such as CCL2, CCL5 and CXCL12 for recruitment from peripheral monocytes/macrophages into the TME at the primary tumor site." (PMID 39135069, 2024). "HLA-DRA also showed a surprising positive correlation with CCL4, CCL5, CXCL9, and CXCL10, indicating its beneficial role in the human immune response through inducing immune cell infiltration and improving tumor clearance in the body." (PMID 38931345, 2024). "Previous studies have shown that tumor-derived CCL2 and CCL5 can attract macrophages that enhance the metastatic capacity of the primary tumor (35, –37)." (PMID 39636862, 2024). "Meanwhile, macrophages can promote tumor invasion and metastasis through secretion of various cytokines (e.g., TGF-β, IL-10, arginase 1) and chemokines (e.g., CCL5, CCL17, CCL18, CCL22)." (PMID 38637499, 2024). "Immunohistochemical staining revealed that AAE intervention significantly decreased the proliferative capacity of tumor cells and increased the expression of multiple chemokines, including CCL2, CCL5, and CCL10." (PMID 39206194, 2024). "In tumour vasculature, the PI3K/AKT/P70S6K pathway is responsible for HIF‐1α to induce VEGF for angiogenesis, suggesting that CCL5 regulates EPC angiogenesis via CCR5/AKT/P70S6K axis." (PMID 38899522, 2024). "Chemotherapeutic treatment of tumor-bearing mice was reported to lead to intratumoral expression of CXCL9, CXCL10, and CCL5 chemokines which facilitate recruitment and infiltration of CD4+ and CD8+ T cells into the tumor bed." (PMID 38360737, 2024). "This combination treatment ICG-001/anti-PD-1 effectively suppresses HCC growth in mice by upregulating the expression of CCL5, and promoting the infiltration of immune cells such as DC and CD8 + T cells in the tumour microenvironment." (PMID 39261716, 2024). "For example, CCL5 binds to the CCR5 receptor on the surface of CTLs, recruiting them to the TME and, ultimately, promoting tumor regression." (PMID 38931345, 2024). "CCL5, while mediating CD8+ chemoattraction, has also been shown to recruit TAMs and to promote tumor growth by influencing TAM polarization towards a pro-tumor phenotype." (PMID 38928238, 2024). "CCL5/SDC-1 receptor-ligand interactions were also present, and are known to promote pro-tumor crosstalk between T cells and malignant cells." (PMID 38064127, 2024). "Our study found that being the most important cells for tumor immunity, CD8T cells secreted more CCL5 compared with other cell types." (PMID 39183447, 2024). "Compared with the control treatment, CCL5 and CXCL10 blockade abrogated the effect of APG-2575 on tumor growth." (PMID 38062129, 2024).
tumor (continued). "Thirdly, TAMs inhibit the recruitment of T cells to tumor sites by producing peroxynitrites and nitrifying CCL2 and CCL5, thereby preventing chemotaxis of CAR-T and other T cells to the tumor, reducing their effectiveness." (PMID 39136031, 2024). "rh-CCL5 significantly promoted the migration of THP-1 and PMBC-derived monocytes in 4 h, which was stimulated by EBV-positive tumour cell CM for 24 h." (PMID 39267775, 2024). "The mRNA levels of the cytokines CCL5, CCL18, and GDF15, as well as the transcription factor IRF4, correlated weakly positively with the tumor volume." (PMID 39272860, 2024). "We investigated associations of a 4-chemokine expression signature (c-Score: CCL4, CCL5, CXCL9, CXCL10) with metrics of antitumor immunity across tumor types." (PMID 37558751, 2023). "STING signaling also generates a chemokine gradient, including CXCL10, CCL5, and CXCL9, that can guide the recruitment and activation of T cells and NK cells within the tumor." (PMID 37627155, 2023). "B1R also regulated the production of the protumorigenic cytokines and chemokines IL-6, IL-8, CXCL11, and CCL5 in GBM, which contributed to tumor progression." (PMID 37627528, 2023). "Tumor cell-derived cytokines (such as IL-6, IL-10, IFN-γ and TGF-β) and chemokines (such as CCL2, CCL5 and CXCL4) are key regulators of macrophage polarization." (PMID 37833255, 2023). "It proved that CCL5 expressed by AdKi67-C3 indeed induced more CAR-T migration in vitro and CAR-T infiltration in tumor mass in vivo." (PMID 37660142, 2023). "Our results indicate that epigenetic priming mediates the rapid secretion of key tumor-derived cytokines known to augment T and NK cell activation and cytotoxicity, including IL-6, IP-10 (CXCL10), KC (CXCL1), and RANTES (CCL5)." (PMID 37627156, 2023). "MSCs can also enhance tumor vascularization by upregulating VEGF and IL-6, and promote the progression and metastasis of cancer by secreting CCL5, CCL7, and TGF-β." (PMID 37666813, 2023). "The pan-HDACi rodempsin was reported to increase the expression of chemokines CCL5 and CXCL9 and 10 by tumor and stromal cells, increasing tumor infiltration with T cells and thereby improving the antitumor immune response." (PMID 38258065, 2023). "Macrophages are relocated to tumor areas and differentiate into TAMs in response to various cytokines, such as IL-34, CSF1, members of VEGFs, and chemokines, such as CCL5 and CCL2." (PMID 37958467, 2023). "Neutrophil cluster 6 also has high expression of Ccl2, Ccl3, Ccl4, Ccl5, and Cxcl2, which are inflammatory mediators involved in MDSC migration to and activation in the tumor microenvironment." (PMID 37483625, 2023). "Some chemokines described in this review, including CCL2, CCL5 and CCL15, can also recruit effector cells (including NK cells, T lymphocytes) that are critical for tumor clearance." (PMID 36173487, 2023). "This correlated with an upregulation of the chemokines CCL5, CCL19, CXCL9, and CXCL10 expression from the tumor." (PMID 38022679, 2023). "In experimental BC models (tumor cells from MMTV-PyMT mice and MCF-7 cells), estradiol enhanced macrophage influx and angiogenesis through increased release of CCL2, CCL5, and VEGF." (PMID 37208442, 2023). "Resultant expression of soluble mediators such as CCL5 and CXCL10 can facilitate recruitment of dendritic cells and immune effector cells into the tumor." (PMID 37079538, 2023). "To investigate the role of CCL5 in PAAD, we conducted a comprehensive analysis of 48 tumor sections using various biomarkers." (PMID 37553567, 2023). "Due to the role of various chemokines (such as CCL2 and CCL5) and cytokines (for example, CSF1 and members of the VEGF family) at the tumor site, monocytes are recruited at the tumor site to form TAMs." (PMID 37111726, 2023). "NLRC3 showed moderate and strong correlations with CCL5, CXCL9, CXCL10, CXCL11, CXCR3, and CCR5, resulting in an increased recruitment of NK cells, TH1 cells, and CD8+ T cells in tumor tissues." (PMID 36808166, 2023).
tumor (continued). "In cutaneous melanoma mouse models, temozolomide increased the expression of CCL5, CXCL9, and CXCL10, resulting in increased T-cell trafficking to the tumor." (PMID 36949946, 2023). "The chemokine CCL5 and its receptor CCR5 are pivotal players in the development of tumor affected by TAMs." (PMID 36173487, 2023). "The results with OV-αCD47-G1 and OV-Cmab-CCL5 illustrate the power of secreted bispecific molecules interacting with Fc receptors to target both the TME and tumor cells." (PMID 37325516, 2023). "Several studies have shown that activation and infiltration of CD8+ cytotoxic T cells and NK cells are reliant on type I interferon (IFN) such as IFNβ, and chemokines such as CCL5 and CXCL10 in the tumor microenvironment." (PMID 37079538, 2023). "In melanoma studies, it has been observed that activation of STING in tumor cells and DCs leads to increased infiltration of NK cells in the tumor microenvironment (TME) through the secretion of CXCL10 and CCL5 cytokines." (PMID 37781382, 2023). "Recruitment of cDC1s into the tumor site is also crucial for their anti-tumor activity and depends on the presence of different chemokines in the TME—such as XCL1, XCL2 and CCL5—mainly produced by NK cells." (PMID 37190135, 2023). "SRC is related to tumor suppressor factors, monocyte-macrophages and T cell chemokines by interacting with IL-15, colony stimulating factor 1 (CSF1), C-C motif chemokine ligand 5 (CCL-5), etc.." (PMID 36902024, 2023). "Current monoculture tumor spheroid models lack the presence of specific cytokines present in the PDAC TIME, such as CCL4/MIP-1β, CCL5/RANTES, CXCL9, and CXCL10 accidentally simulating an immune silent or excluded PDAC TIME." (PMID 37519820, 2023). "Chemokines produced by tumor cells, immune cells, and tumor stromal cells, including CC­chemokine ligand 2 (CCL2), CCL5, CXC­chemokine ligand 12 (CXCL12, also known as SDF1) and CXCL1, are involved in this process." (PMID 36824409, 2023). "Intratumor microbiota such as Lachnoclostridium genus, Gelidibacter, Flammeovirga, and Acinetobacter induce tumor cells to secrete chemokines CXCL9, CXCL10, and CCL5, thereby recruiting CD8+ T cell infiltration." (PMID 37937304, 2023). "Pre-treatment with oxaliplatin and cyclophosphamide induced a pro-inflammatory tumor microenvironment and enhanced secretion of CCL5, CXCL9, CXCL10, and CXCL16 by tumor-infiltrating macrophages, leading to enhanced ROR1-CAR-T cell infiltration." (PMID 36949946, 2023). "IL6 secreted by tumor cells can activate STAT3 signaling, inducing HIF-1⍺ and VEGF and conditioning lymphatic endothelial cells to express CCL5." (PMID 37440925, 2023). "Tumor cells and stroma, which make up the hypoxic core of the tumor microenvironment, promote the production of VEGF, CCL2, CCL5, CSF-1, EMAP-II, endothelin-2, SEMA3A, oncostatin M, and eotaxin." (PMID 37056346, 2023). "Exposure of microglial cells to glioblastoma cell-derived EVs revealed an upregulation of the expression of the pro-tumor factors CXCL1/10, CCL2/CCL5 and IL-6 as well as an increase in their own proliferation." (PMID 37700840, 2023). "Conditioned tumor cell medium treated with 10 μM 5-aza showed upregulation of 4 key cytokines—IL-6, IP-10 (CXCL10), KC (CXCL1), and RANTES (CCL5)—which activate both adaptive and innate immune responses." (PMID 37627156, 2023). "Surprisingly, we found a higher proportion of macrophage C4 in brain metastatic tissues, and this macrophage subpopulation was highly expressed in genes that promote tumor invasion and metastasis, such as CSTB, MMP9, CCL5, and MIF." (PMID 37715019, 2023). "In TME, CAFs can regulate tumor progression and immunity by producing growth factors, cytokines, and chemokines, including CCL2, CCL5, CSF1, CXCL5, CXCL9, CXCL10, and CCL5." (PMID 37206921, 2023).
tumor (continued). "Consistent with their M1 differentiation, the macrophages upregulated expression of the chemotactic factors Ccl5 and Cxcl10, responsible for recruiting T lymphocytes (in this instance CAR T cells) into the tumor stroma." (PMID 37660083, 2023). "Mesenchymal stem cells promote tumor metastasis by secreting chemokine ligand 5 (CCL5) and TGF-β, which are responsible for the EMT of tumor cells and the maintenance of stem cell properties." (PMID 37900137, 2023). "CCL5, CCL-11, CXCL9, and CXCL10 are postulated as the main drivers in eosinophil-mediated tumor cell necrosis." (PMID 36427017, 2023). "In a similar context, the knockdown of CCL5 from CT26 (mouse colon tumor cells) inhibited apoptosis of CD8+ and consequently reduced the size of the tumor in the mice model." (PMID 37987366, 2023). "ILC2 triggered by IL33 expresses CCL5 selectively, attracts CD103+ DCs into tumor, and stimulates CD8+ T cells to induce therapeutic tumor immunity." (PMID 37937304, 2023). "IE1 tumors also had increased scores for chemotactic interactions, mainly mediated by CCL3, CCL4, CCL5, and CXCL9, suggesting a more dynamic immune environment with increased potential for recruitment of cells from outside the tumor." (PMID 36609566, 2023). "The correlation coefficient between the density of CCL5-positive cells and AREG-positive cells was 0.31, indicating that CCL5 and AREG were present in the tumor microenvironment." (PMID 37553567, 2023). "Elisa data showed that CCL5 was higher in both right and left tumor of AdKi67-C3 + CAR-T group and IFN-γ was higher in all AdKi67-DsRed, AdKi67-CCL5, AdKi67-C2 or AdKi67-C3 combined with CAR-T group." (PMID 37660142, 2023). "The chemokines, such as CXCL12, CCL20, CCL5, CCL28, and CCL2/22, guide the Treg homing to the tumor." (PMID 36479842, 2023). "Upregulation of several chemokines, including CCL3, CCL5, CCL22, CXCL9, CXCL10, and CXCL11, has been described to play different roles with effects depending on tumor type and other TME factors." (PMID 36831435, 2023). "This immunomodulatory effect was not restricted to oxaliplatin, other platinum-based drugs, such as carboplatin, have also increased tumor CD8+ T cell populations and enhanced CCL5 and CXCL10 mRNA levels in lung cancer cells." (PMID 36949946, 2023). "Both the CCL5 and CCL2 chemokines recruit MDSCs to the tumor site, and the CAF-MDSC axis affects ROS levels." (PMID 37430270, 2023). "Activation of Notch signaling in macrophages led to secretion of CCL5, one of the genes found to be upregulated in our metastatic cell collection and led to increased EMT and tumor cell migration." (PMID 37202533, 2023). "For instance, MSCs in the tumor stroma, in response to signals released by cancer cells, were found to secrete CCL5/RANTES; CCL5 then acts inversely on cancer cells and stimulates invasive behavior." (PMID 36674806, 2023). "As detected by qPCR, significantly increased mRNA expression levels of CXCL1, CXCL2, CCL5, CXCL10, and IFN-β were detected in tumor tissues isolated from the shIDH3α + CDDP + PD-L1 group compared to the control+CDDP+PD-L1 and shIDH3α groups." (PMID 36980689, 2023). "This phenomenon enhances the secretion of CCL5 in CAFs, which bind to CCR5 present on the tumor cells to induce tumor cell invasion." (PMID 37868988, 2023). "It is noteworthy that cytokines such as CCL2, CCL5, and CSF1 were found to be involved in the attraction of MDSCs to the tumor site." (PMID 37033447, 2023). "Numerous studies have demonstrated that the CCL5/CCR5 axis is important for cancer growth, migration, and establishment of an immunosuppressive tumor microenvironment." (PMID 37845206, 2023). "Tumor cell-autonomous CD73 is found to facilitate Treg recruitment, in which CCL5 is identified as a significant downstream effector of CD73 using integrated proteomic and transcriptomic analyses." (PMID 37291128, 2023).
tumor (continued). "Six out of 18 chemokines/cytokines assessed were significantly decreased in the ascites from NLRC5+ tumor-bearing mice, including IL-6, IL-10, IL-12, CXCL10, CCL5, and to a greater extent, CCL2." (PMID 38235131, 2023). "In vitro, it was found that CCL5 promoted the migration of CRC cells and the proliferation of tumor cells in a dose-dependent manner." (PMID 37141250, 2023). "Regarding tumor progression, the CCR5/CCL5 interaction is involved in the activation of the Akt pathway, which is related to the development of HCC." (PMID 38133557, 2023). "In pt115, the genes that were most upregulated in the expanded REP TIL clonotypes in the original tumor were NKG7, CCL5, and CD8A, but also those related to cytotoxicity, such as GZMB/H/K." (PMID 37484198, 2023). "Eosinophil commitment to Th1 response was previously shown as well where these leukocytes produced CXCL9, CXCL10, CXCL11, and CCL5 under the effect of TNF-α and IFN-γ, which recruit T and NK cells to eradicate tumor." (PMID 37587450, 2023). "MSCs can also secrete chemoattractants, including CXCL1, CCL5, CXCL5, CXCL8 and CXCL7, which promote tumor cell migration to metastatic lesions." (PMID 36926687, 2023). "It is generally accepted that a decline in production of chemokines such as CCL5 and CXCL9/10/11 in tumor stromal cells contributes to tumor promotion and even to ICI resistance." (PMID 37736764, 2023). "Under the influence of GBM, GAMs are a major source of inflammatory cytokines (e.g., IL-1β, IL-8, IL-10) and chemokines (e.g., CCL2, CCL4, CCL5) that support GBM growth and mitigate anti-tumor immune function." (PMID 37368789, 2023). "CCL5, IFN-γ, or IL-12 expression in tumor cells infected with indicated oncolytic adenovirus was also assayed by Elisa." (PMID 37660142, 2023). "CXCL10 and CCL5 chemokines were reported to stimulate CD4+ and CD8+ lymphocyte migration into the intra-tumor and stromal compartment, and CCL20 drove brain infiltration of Treg cells." (PMID 38239560, 2023). "This includes expression of type 1 interferons and T-cell-recruiting chemokines [C-C Motif Chemokine Ligand 5 (CCL5), C-X-C Motif Chemokine Ligand 10 (CXCL10)], leading to a higher level of tumor-infiltrating T-cells." (PMID 35327359, 2022). "Meanwhile, the oHSV expressing cytokine IL-12, and chemokine CCL5 as well as checkpoint inhibitor anti-PD-1 antibody, further augment CAR T cell trafficking to the tumor site and their antitumor activities." (PMID 36353540, 2022). "CD103+ cDC1s are recruited to the tumor site by chemokines such as CCL4 and CCL5 secreted by tumor cells." (PMID 36275666, 2022). "Notch1 contributes to an immune-suppressive tumor microenvironment by inhibiting the expression of SNAP23 and overexpression of IL-6, IL-8, and CCL5 downstream of the pathway, thus affecting the efficacy of immune-checkpoint inhibitors." (PMID 36119081, 2022). "The present study revealed that CRC tumor buds secreted high levels of CCL5, which recruited fibroblasts through CCR5-SLC25A24 signaling and led to the development of a characteristic fibroblast cluster around tumor buds at the invasive front." (PMID 35241150, 2022). "A recent immunohistochemistry and RNA-sequencing meta-analysis of resectable and advanced PDAC specimens showed a positive correlation between CCL5, CXCL9 and CXCL10 and CD8+ T cells infiltration in close proximity to tumor cells." (PMID 35954489, 2022). "In parallel, treatment of the tumor cells by i-Ras also led to a reduction of their extracellular levels: 35–40%, 90–95% and 75–85% inhibition of CXCL8, CCL2 and CCL5, respectively." (PMID 35205789, 2022). "In a murine melanoma model, NK cells secreted the chemokines CCL5 and XCL1, recruiting cDC1 dendritic cells into the tumor microenvironment, leading to controlled tumor growth." (PMID 35203609, 2022). "g, CCL1, CCL5, CCL7, CXCL8, and CXCL12) drive the recruitment of MDSCs to OC tumor sites via the CCR2, CXCR4, and CCR5 axes." (PMID 36532066, 2022).